APOL3 (apolipoprotein L3)
Diseases named in the same sentence as APOL3 in open-access papers:
APOL3 is named in the same sentence as 39 diseases in open-access papers, as found by Europe PMC text mining. Sharing a sentence is not in itself a finding about the gene and the disease. The quoted sentences say what the papers report.
colorectal cancer (3 papers, 2023 to 2025). A primary or metastatic malignant neoplasm that affects the colon or rectum. "In addition, APOL3 also regulates the tumor microenvironment in colorectal cancer by regulating the immune activity of CD8+ T cells through LDHA192." (PMID 40959280, 2025). "Increased APOL3 expression inhibited colorectal cancer cell proliferation and promoted ferroptosis." (PMID 40959280, 2025).
prostate carcinoma (3 papers, 2019 to 2023). A carcinoma that arises from epithelial cells of the prostate gland. "Moreover, a case-control study has shown the association between a SNP within the APOL3 locus and prostate cancer risk." (PMID 31303963, 2019).
breast carcinoma (2 papers, 2022 to 2024). "Nevertheless, the functions and underlying mechanisms of APOL3 in breast cancer have yet to be elucidated." (PMID 39006089, 2024). "Overexpression of APOL3 suppressed breast cancer cell proliferation, induced cell cycle disruption." (PMID 39006089, 2024). "APOL3, APOL4, NR1H3, OSBPL1A, MAP2K6, and ZDHHC8 were protective genes for breast cancer prognosis." (PMID 35919504, 2022).
diabetes (2 papers, 2023 to 2024). "APOL3 was found to be involved in cell adhesion molecular cams, chemokine-signaling pathways, type 1 diabetes mellitus, and fatty acid metabolism by KEGG pathway in the GSE14520 cohort." (PMID 38017264, 2023). "APOL3 was found to be involved in cell adhesion molecular cams, type 1 diabetes mellitus, chemokine signaling pathways, and fatty acid metabolism by KEGG pathways in the TCGA cohort." (PMID 38017264, 2023).
kidney damage (2 papers, 2024). "A previous study on the interactions between APOL1 and APOL3 suggested that deletion of APOL3 triggers intracellular actomyosin reorganization, increasing susceptibility to kidney disease through APOL1-induced podocyte dysfunction and kidney damage." (PMID 39163132, 2024). "This probably explains why the prominent pathology resulting from interference with APOL1 and APOL3 functions, as occurs following the expression of the APOL1 C-terminal variants G1 or G2, is nephropathy." (PMID 39768205, 2024).
Obesity (2 papers, 2020 to 2025). Accumulation of substantial excess body fat. "Top genes differentially methylated between these cohorts included the obesity-protective MFAP2 gene as well as cancer risk susceptibility genes APOL3 and RNASEL." (PMID 39844333, 2025). "A recent study reported the association of MYTIL (myelin factor 1-like), an early-onset obesity-related gene; APOL3 (apolipoprotein L3), lipid-transport and metabolism-associated genes; and STIM1 (stromal interaction molecule 1) involved in catty body weight gain." (PMID 32904540, 2020).
viral infection (2 papers, 2021 to 2024). "In conclusion, interference with APOL1 or APOL3 activities can affect viral infection through their influence on virus replication, but also through their involvement in antiviral signaling and the building of the immune response." (PMID 39768205, 2024). "In addition, a role linked to viral infection was suggested for APOL1 and APOL3, given the strong induction of their expression through the viral inflammatory TLR3/TRIF pathway, and the linkage of G1‐ or G2‐induced kidney disease with HIV infection." (PMID 32530132, 2021). "Therefore, individuals devoid of APOL1 or APOL3, or expressing the APOL1 variants G1 or G2, may exhibit defects in resistance to viral infection, but also reduced ability to respond to pathogens in general." (PMID 39768205, 2024). "Following this hypothesis, kidney disease linked to APOL3 KO would not be expected to exhibit association with viral infection." (PMID 32530132, 2021).
acute myeloid leukemia (1 paper, 2019). Acute myeloid leukemia (AML) is a group of neoplasms arising from precursor cells committed to the myeloid cell-line differentiation. "The high expression of APOL3 was reported to predict worse clinical outcome in patients with acute myeloid leukemia." (PMID 31212865, 2019).
cardiomyopathy (1 paper, 2024). A disease of the heart muscle or myocardium proper. "Notably, our research has established a causal linkage between the APOL3 protein and cardiomyopathy, while the F11 and LRP4 proteins have been identified as potential culprits for ischemic stroke." (PMID 38820305, 2024). "APOL3, LRP4, and F11, on the other hand, have specific effects on cardiomyopathy and ischemic stroke, respectively, all classified as highly recommended level protein targets." (PMID 38820305, 2024). "APOL3, LRP4, and F11, on the other hand, have specific effects on cardiomyopathy and ischemic stroke, respectively." (PMID 38820305, 2024).
chronic kidney disease (1 paper, 2024). Impairment of the renal function secondary to chronic kidney damage persisting for three or more months. "The common coding variant APOL3 p.Q58* is a genetic modifier of chronic kidney disease risk in individuals monoallelic for APOL1 G1/G2 carrier status in individuals of African ancestry." (PMID 39163132, 2024).
Cirrhosis (1 paper, 2023). A chronic disorder of the liver in which liver tissue becomes scarred and is partially replaced by regenerative nodules and fibrotic tissue resulting in loss of liver function. "Nomograms were constructed using sex, cirrhosis, BCLC stage, APOL2, APOL3 and APOL6 expression for RFS." (PMID 38017264, 2023). "For the GSE14520 cohort, nomograms were constructed using tumor size, cirrhosis, α-fetoprotein (AFP), Barcelona Clinic Liver Cancer (BCLC) stage, APOL3 and APOL6 expressions for OS." (PMID 38017264, 2023). "Small tumor size; female sex; lack of cirrhosis; BCLC stage 0; high expression of APOL2, APOL3 and APOL6; and low AFP levels indicated higher survival rate in the GSE14520 cohort." (PMID 38017264, 2023).
colon cancer (1 paper, 2023). "Moreover, we transfected RKO colon cancer cells with APOL1-KO, APOL2-KO, APOL3-KO, APOL4-KO and APOL6-KO." (PMID 36923931, 2023).
cutaneous melanoma (1 paper, 2019). A primary melanoma arising from atypical melanocytes in the skin. "Surprisingly, APOL3, which encoded Apolipoprotein L3 was found to be the 58th most closely correlated gene with patient survival in cutaneous melanoma, which was as high as HLA class II genes." (PMID 31212865, 2019). "In this study, survival analysis showed higher expression level of HLA class II co-expressed genes, especially APOL3, CD74, C1QA and C1QB, were associated with better prognosis in cutaneous melanoma." (PMID 31212865, 2019). "However, whether APOL3 directly bridge the relation between cutaneous melanoma and metabolic syndrome cannot be clarified from the results of the present study." (PMID 31212865, 2019). "However, no study related to the functional role of APOL3 in cutaneous melanoma has been reported." (PMID 31212865, 2019).
endothelial dysfunction (1 paper, 2020). In vascular diseases, endothelial dysfunction is a systemic pathological state of the endothelium (the inner lining of blood vessels) and can be broadly defined as an imbalance between vasodilating and vasoconstricting substances produced by (or acting on) the endothelium. "Increased ApoL3 in PE may be a compensatory response to endothelial dysfunction." (PMID 32953262, 2020).
hyperlipoproteinemia type I (1 paper, 2023). "For instance, rs132642 in APOL3 had no annotation in ClinVar, and rs328 in LPL is annotated as benign in the phenotype hyperlipoproteinemia type I. This mutation truncates the last two codons of the protein." (PMID 37065472, 2023).
Hypertension (1 paper, 2016). The presence of chronic increased pressure in the systemic arterial system. "We identified novel mRNA-microRNA pairs potentially involved in hypertension-related pathways and differently-expressed, including MCL1/miR-20a-5p, APOL3/miR-4763-5p, PLD1/miR-4717-3p, and PLD1/miR-4709-3p." (PMID 27779208, 2016).
insomnia (1 paper, 2023). A sleep disorder characterized by difficulty in falling asleep and/or remaining asleep. "In this study, the expression levels of C2CD2L, SPINT2, APOL3, PKNOX1, and A2M exhibited clear associations with most of the 22 immune cells tested, thus suggesting that these genes may participate in the development of insomnia by regulating multiple immune cells." (PMID 38090272, 2023). "The expression levels of C2CD2L in insomnia samples were significantly lower than those in normal samples, and APOL3 and PKNOX1 showed no significant changes in the two groups." (PMID 38090272, 2023). "qRT-PCR was performed to determine the expression levels of C2CD2L, APOL3, and PKNOX1 in rats with and without insomnia." (PMID 38090272, 2023).
liver fibrosis (1 paper, 2025). "I conclude that inactivation of APOL3 could be responsible for both ER stress and increased vesicle exocytosis underlying liver fibrosis." (PMID 40503184, 2025). "In this regard, it would be interesting to investigate if individuals naturally lacking APOL3 following gene mutation, suffer liver fibrosis even without TGF-β stimulation." (PMID 40503184, 2025).
oral squamous cell carcinoma (1 paper, 2023). "In addition, APOL3 is differentially expressed in tumors and controls in oral squamous cell carcinoma." (PMID 38017264, 2023).
preeclampsia (1 paper, 2021). Preeclampsia is a hypertensive disorder of pregnancy that is characterized by new-onset hypertension with proteinuria presenting after 20 weeks of gestation, and depending on mild or severe forms may initially present with severe headache, visual disturbances, and hyperreflexia. "The involvement of APOL3 in the control of cellular adherence and motility might possibly account for altered trophoblast invasion linked to preeclampsia." (PMID 32530132, 2021).
renal failure (1 paper, 2025). "Prime among them is APOL3, which in one of the two renal-risk variant discovery papers, also showed a renal failure risk association of null variant of APOL3 Q58X nonsense (rs11089781)." (PMID 40643530, 2025).
Theileria infection (1 paper, 2023). "In our list Apolipoprotein 3 (APOL3) is induced by Theileria infection and down-regulated upon attenuation (log2 Fold Change was − 1.09; p adj value < 0.001) which suggest its implication in the attenuation process." (PMID 37875584, 2023).
tumor (13 papers, 2021 to 2025). "To verify why low APOL3 expression is associated with dampened antitumor function and poor prognosis, we analyzed the relationship between APOL3 and cytotoxic cytokine-associated gene expression in tumor-infiltrating CD8+ T cells in CRC patients from TCGA database." (PMID 36923931, 2023). "In CD8+ T cell-based studies, Apolipoprotein L3 (APOL3) was found to enhance the tumor-related immune response of CD8+ T cells." (PMID 40959280, 2025). "Together, these data demonstrated that alteration of APOL3 of CT26 played influence on tumor volume through tumor microenvironment modulation." (PMID 36923931, 2023). "Taken together, these results further suggested the molecular mechanism by which APOL3 controls tumor proliferation, ferroptosis and anti-tumor immunity via promoting ubiquitylation-related degradation of LDHA in CRC." (PMID 36923931, 2023). "Early tumor stage, radical resection, low APOL3 expression, high APOL4 and APOL6 expressions, vascular invasion and HBV infection indicated higher survival rates in the TCGA cohort." (PMID 38017264, 2023). "Overall, abnormal levels of APOL3 appeared to consistently exert tumor suppressor tendencies in CRC cell lines." (PMID 36923931, 2023). "Consistent with above findings, tumor volume analysis indicated that APOL3-OE of CT26 with treatment of RSL3 significantly increased the antitumor ability of PD-1 inhibitor in vivo and this effect can be diminished by co-overexpression of LDHA." (PMID 36923931, 2023). "Then, based on in vivo analysis and tumor specimen, we discovered the APOL3-LDHA axis can facilitate the tumor ferroptosis and cytotoxic ability of CD8+ T cells through increased IFNγ and decreased lactic acid concentration." (PMID 36923931, 2023). "In vivo animal experiments demonstrated that APOL3 overexpression can inhibit tumor proliferation." (PMID 39006089, 2024). "Hence, overexpression of APOL3 may serve as an effective strategy to selectively induce ferroptosis in tumor cells, sparing immune cells within the TME." (PMID 40285867, 2025). "Finally, 8 genes related to anti-tumor immunity were obtained, which were APOL3, CCL5, CD8A, CD8B, CXCL9, GZMA, GZMK and PRF1.We found that the m6A regulatory factors YTHDC1, YTHDC2, and WTAP were positively correlated with m6A, while IGF2BP3 was negatively correlated." (PMID 34737950, 2021). "APOL3, by targeting L-lactate dehydrogenase A (LDHA) for degradation through ubiquitination, can potentiate tumor ferroptosis and the cytotoxic potential of CD8 + T cells." (PMID 40285867, 2025). "APOL3 plays a role in the ubiquitination of LDHA, thereby increasing tumor cell sensitivity to the ferroptosis-inducing protein RSL3." (PMID 38853203, 2024). "Nomograms were constructed for tumor stage, radical resection, HBV infection, vascular invasion, APOL3 and APOL4 expression for RFS." (PMID 38017264, 2023). "Apolipoprotein L3 (APOL3) has been identified as a key modulator, positively affecting sensitivity to ferroptosis and improving CD8+ T cell-mediated anti-tumor responses in CRC." (PMID 37958383, 2023). "In light of our above findings of APOL3-LDHA axis, we performed both in vitro and in vivo analysis to demonstrate the effect of APOL3-overexpressed CRC cells on the anti-tumor ability of CD8+ T cell." (PMID 36923931, 2023). "Recently, APOL3 was identified as the top protein in a screening assay for ferroptosis-related CD8 + T cell infiltration in mismatch repair-proficient CRC, implicating it as an antitumor immunity-promoting tumor suppressor." (PMID 39844333, 2025). "Additionally, the APOL3-LDHA pathway facilitates the expression of IFN-γ, thereby augmenting anti-tumor immunity." (PMID 38853203, 2024). "Finally, IHC analysis based on CRC specimen revealed that APOL3 expression was positively correlated with CD8+ T cell infiltration with R2 of 0.58 and negatively correlated with tumor LDHA expression with R2 of 0.17." (PMID 36923931, 2023).
tumor (continued). "Not surprisingly, APOL3-OE+RSL3+PD1 cohort tumor showed the largest IFNG expression and percent of IFNγ of CD8+ T cells compared to another 5 cohorts." (PMID 36923931, 2023). "Results showed HCT116 APOL3-knockout cells promoted tumor growth by 42% when compared to their negative controls." (PMID 36923931, 2023). "In addition to the robust induction of type I and type III interferons, expression of APOA1, APOL1, APOL3, and CH25H was increased from 10 to >50-fold, depending on the cell line (C1 or C2) from which the tumor originated." (PMID 34983824, 2022). "Results suggest that AKAP12, APOL3, CXCL13, CXCL9, GBP4, and LRIG1 may act as tumor suppressors." (PMID 35677536, 2022).
cancer (6 papers, 2019 to 2025). A tumor composed of atypical neoplastic, often pleomorphic cells that invade other tissues. "Mechanically, APOL3 can promote ubiquitylation-related degradation of LDHA, APOL3-LDHA axis inhibits cancer cell proliferation, promote ferroptosis and CD8+ T cells' antitumor ability." (PMID 36923931, 2023). "It is well known that APOL3-controlled NCS-1 promotes cancer cell motility, metastatic spread, and survival." (PMID 35919504, 2022). "Overexpression of APOL3 inhibited cancer cell growth in CRC cells, while knockout of APOL3 promoted cancer cell proliferation." (PMID 36923931, 2023). "Up-regulated expressions of the hypo-methylated gDMs in cancer were observed for OAS2, MX2, APOL3, ABHD8, RASSF1, SIGIRR, and SPRED2." (PMID 36329447, 2022).
kidney disease (5 papers, 2021 to 2025). "The rise to high frequency of a null variant of APOL3 in African ancestry populations (despite the association of that variant with kidney disease), suggests a context specific adaptive advantage in what is otherwise considered a protective gene product." (PMID 40643530, 2025). "Our approach identified multiple AFR-specific protein-altering variants in the APOL gene family implicated in kidney disease risk, including a stop-gain variant in APOL3 that increases the risk of CKD primarily in persons carrying 1 APOL1 G1/G2 risk allele." (PMID 39163132, 2024). "Accordingly, natural APOL3 disruption due to gene mutations was linked to kidney disease, confirming that APOL3 is required for proper podocyte activity." (PMID 39451256, 2024). "However, the APOL3 stop-gain variant rs11089781 (p.Q58*) remained nominally significantly associated with increased risk for renal disease." (PMID 39163132, 2024). "We found that the APOL3 variant was strongly associated with decreased minimum estimated glomerular filtration rate (eGFR; P = 2.17 × 10–7, n = 10,435) and increased maximum creatinine (P = 3.85 × 10–6, n = 10,435), consistent with increased risk for renal disease." (PMID 39163132, 2024). "This truncating variant contributed the most risk for CKD in patients monoallelic for APOL1 G1/G2, suggesting an epistatic interaction and a potential protective effect of wild-type APOL3 against APOL1-induced kidney disease." (PMID 39163132, 2024). "The phenotype of APOL3 KO or APOL1Δ podocytes provides a clear confirmation that APOL1 nephropathy can occur independently from APOL1 cation pore-forming activity." (PMID 39451256, 2024). "Our genetic data indicate that wild-type APOL3 may play a protective role in CKD, given that the APOL3 p.Q58* risk variant is very likely to be loss of function and confers increased risk for renal disease." (PMID 39163132, 2024). "Consistent with the observation that natural APOL3 KO individuals suffer kidney disease, the cellular phenotype observed experimentally in cultured APOL3 KO podocytes resembled the podocyte phenotype of transgenic mice suffering kidney disease due to G1 or G2 expression." (PMID 39451256, 2024). "This association was consolidated by two independent follow-up studies that showed significant association between a lack of functional APOL3 and increased risk for kidney disease, with only one of these having the power to also demonstrate an APOL1 interaction effect." (PMID 40643530, 2025). "Since natural APOL1 KO does not induce kidney disease, the most conservative explanation of these different observations is a negative effect of the APOL1 variants on APOL3." (PMID 32530132, 2021).
infection (3 papers, 2023 to 2025). The state of being infected such as from the introduction of a foreign agent such as serum, vaccine, antigenic substance or organism. "Specifically, human APOL1 and APOL3 appear to control membrane remodeling linked to pathogen infection." (PMID 39768205, 2024). "In conclusion, through their key involvement in mitophagy and apoptosis, APOL1 and APOL3 contribute to avoiding the detrimental effects of infection-induced inflammation on mitochondrial function." (PMID 39768205, 2024). "Thus, APOL1 and APOL3 are involved in distinct activities controlling membrane dynamics in response to pathogen infection and, consequently, innate immunity induction." (PMID 39768205, 2024). "We also detected enhanced transcription of the apolipoproteins APOL1, APOL3, and APOL4, which also act as immune regulators in response to infection." (PMID 41416938, 2025).
cardiovascular diseases (1 paper, 2024). "Apolipoprotein L3 (APOL3), a member of the apolipoprotein family, has been implicated in the pathogenesis of cardiovascular diseases." (PMID 39006089, 2024).
APOL3 also shares sentences with these, for which no sentence is quoted: Alzheimer disease (1 paper); bacterial infections (1); bladder cancer (1); eosinophilia (1); ischemic stroke (1); liver cancer (1); melanoma (1); metabolic syndrome (1); metastatic tumors (1); oral carcinoma (1); papillary thyroid carcinomas (1); type 1 diabetes mellitus (1).